LAMC2 (laminin subunit gamma 2)
Diseases named in the same sentence as LAMC2 in open-access papers (continued):
Sharing a sentence is not in itself a finding about the gene and the disease.
tumor (continued). "Promoter methylation was lower in PAAD than normal pancreatic tissues for all three genes (LAMA3 normal β:0.43, tumour β:0.34, p = 2.8 × 10−9; LAMB3 normal β:0.65, tumour β:0.53, p = 8.6 × 10−7; and LAMC2 normal β:0.44, tumour β:0.38, p = 0.04)." (PMID 37779898, 2023). "Overall, these results suggested that not only are LAMC2 and EGFR positively correlated in protein expression levels, knocking down either of the two can directly hinder the tumor-promoting activity and function of the other." (PMID 37542131, 2023). "To corroborate these results in vivo, we subcutaneously injected control, LAMC2-KD, as well as LAMC2-KD + EGFR A549 cells into 4-week-old male BALB/c-nude mice, and evaluated real-time tumor progression using fluorescence imaging." (PMID 37542131, 2023). "Mechanistically, ZNF750 has been reported to mediate tumor-suppressive roles by regulating the expression of various downstream genes, such as TINCR, LAMC2, DANCR, FGF14, and SNAI1." (PMID 37365152, 2023). "These analyses identified that LAMA3, LAMB3, and LAMC2 expression levels are increased at the mRNA and protein levels in PAAD tumours with evidence of co-regulation." (PMID 37779898, 2023). "The findings presented here show that LAMA3, LAMB3, and LAMC2 are frequently upregulated at the gene and protein levels in PAAD tumours compared with controls and that these increases are related to worse survival outcomes." (PMID 37779898, 2023). "For the first time, this approach now enabled us to explore the behavior of LAMC2-EGFP+ cells in intact tumors, and helped us to demonstrate directly how this cell population contributes to PDAC tumor cell growth and dissemination." (PMID 36289544, 2022). "Other highly upregulated genes with tumor suppressor and/or cell cycle inhibitory activities are LAMB3, LAMC2, and IL1RN, which were increased by 10- to 15-fold." (PMID 34349241, 2022). "In this study, we revealed that OSCC-CSC-sEVs transferring the lncRNA UCA1 promote M2 macrophage polarization via a LAMC2-mediated PI3K/AKT axis, thereby facilitating tumor progression and immunosuppression." (PMID 36483681, 2022). "In conclusion, our results indicated that OSCC-CSC-sEV transfer of UCA1 promotes M2 macrophage polarization via a LAMC2-mediated PI3K/AKT axis, thus facilitating tumor progression and immunosuppression." (PMID 36483681, 2022). "The contribution of LAMC2 to PDAC tumorigenicity was explored in vitro by tumor cell invasion, migration, sphere-forming and organoids assays, and in vivo by tumor growth and metastatic assays." (PMID 36289544, 2022). "Laminin subunit gamma 2 (LAMC2), enriched in most of the KEGG signaling pathways in present study, was found to promote tumor proliferation, metastasis, and vascular regeneration through ECM-receptor interaction and focal adhesion." (PMID 35938013, 2022). "Other highly upregulated genes with tumor suppressor and/or cell cycle inhibitory activities are laminin-5 (LAMB3, LAMC2) and IL1RN, which were increased by 10- to 15-fold." (PMID 34349241, 2022). "LAMC2 was upregulated in metastasis epithelial cells, while CDH1 (E-cadherin) was faded in metastasis p-EMT tumor cells." (PMID 35742914, 2022). "Histological analyses revealed that the tumor xenografts derived from LAMC2-EGFP+-clones displayed a glandular organization and increased desmoplasia compared with tumor xenografts derived from EGFP− cells." (PMID 36289544, 2022). "LAMC2 together with laminin subunit beta-3 (LAMB3) and laminin subunit alpha-3 (LAMA3) constitutes laminin-332, which is secreted by epithelial tumor cells, thereby regulating cancer invasion." (PMID 34612783, 2021). "The results showed that relative to normal samples, proteins (LAMC2, HMGA1, CSTB) were significantly upregulated in tumor tissues." (PMID 34732701, 2021). "The tumor suppressor miR-200 affects EMT and tumor cell metastasis by modulating the cell adhesion molecule E-cadherin and the ECM proteins COL6A1, LAMA5, LAMB2, LAMC2, and Fibronectin." (PMID 34769264, 2021).
tumor (continued). "The interaction of RUNX2 and LAMC2 with the PI3K/AKT and MAPK signaling pathways can act as a driving force in controlling tumor progression." (PMID 34606473, 2021). "It has been shown that the MMP7, LAMC2, and EGFR expressions were correlated with tumor aggressiveness, advanced T grade, and tumor stage in GC tumors." (PMID 32467737, 2020). "LAMC2, an isoform of the laminin family, and the KRT14, KRT16, and KRT17 hemi-desmosomal proteins play crucial roles in tumor cell stability and filament formation anchorage, migration, and proliferation." (PMID 32922662, 2020). "Subsequently, the protein levels of LAMC2 and GSN were respectively down-regulated and up-regulated in tumor tissue with the Human Protein Atlas (HPA) database." (PMID 32640634, 2020). "In PDAC tumor tissues, the expression of LAMA3 and LAMC2 are upregulated with a favorable ability of distinguishing between PDAC and non-tumor tissues, which is of a prognostic value for PDAC patients." (PMID 31182680, 2019). "Our results indicate that LAMC2 expression in GSE102238 tumor tissues is higher than that of paracancer tissues of PDAC and patients who harbored high levels of LAMC2 expression had a poor prognosis." (PMID 31182680, 2019). "Higher levels of miR-197 via downregulation of CD82 in coordination with lower levels of miR-622 via upregulation LAMC2 in GC activate EGFR-ERK1/2 signaling, thus having a role in promoting tumor cell invasion and metastasis." (PMID 28252644, 2017). "Several studies showed Laminin 332 (LAMA3, LAMB3 and LAMC2) to be highly expressed in HNSCC and foster tumor invasiveness, an effect that is reversed when the laminins are repressed by microRNA‐29s." (PMID 27596625, 2016). "Therefore, we used publicly available spatial transcriptomic (ST) data to interrogate sub-localizations of fDEGs in tumor core (TC), and leading edge (LE) of oral SCC (external dataset GSE208253), as exemplified for ITGB4, LAMA3, LAMB3, and LAMC2." (PMID 40121428, 2025). "A group of genes, including collagen type I alpha 1 (COL1A1), fibronectin 1 (FN1), laminin subunit gamma 2 (LAMC2), periostin (POSTN), transforming growth factor beta induced (TGFBI), are involved in extracellular mesenchymal organization and affect tumor behavior, akin to our findings." (PMID 40303998, 2025). "We found that the expression of LAMC2, SLC6A14 and CTSE was distinctly increased in PC specimens and exhibited a dysregulated level in many types of tumors, suggesting their important function in tumor progression." (PMID 38267509, 2024). "Additionally, the overexpression of LAMC2 has been observed to induce EMT, consequently improving tumor cells' invasive and migratory capacities." (PMID 38703300, 2024). "Furthermore, only faint LAMC2 staining was noticed in hepatocytes, while weak and medium LAMC2 staining was observed in HCC tumor tissues." (PMID 38526177, 2024). "Moreover, we performed pan-cancer assays and found that LAMC2, CTSE and SLC6A14 exhibited a dysregulated level in many types of tumors, highlighting their potential function in tumor progression." (PMID 38267509, 2024). "LAMC2 IHC staining was very strong in most iCCA tumor tissues, but no staining in normal bile duct cells or other non‐tumor environment cells." (PMID 38526177, 2024). "Previously, several studies have reported the function of LAMC2 and SLC6A14 in tumor progression." (PMID 38267509, 2024). "Consistent with LAMC2 promoting EGFR translation, EGFR IHC staining in Cohort 4 showed a significantly higher staining score in iCCA tumors compared to bile ducts (p < 0.001) and a positive correlation with LAMC2 staining in iCCA tumor tissues (p = 0.05)." (PMID 38526177, 2024).
tumor (continued). "In this study, we found that the LAMC2-expressed cells and EMP1-expressed cells may be the same cell subset named EP1, which initiates tumor metastasis." (PMID 38818308, 2024). "The construction of the protein–protein interaction network provided additional insight into the functional roles of the selected genes, pinpointing LAMC2, LAMA3, and VEGFC as central nodes that could play crucial roles in tumor development and progression." (PMID 39766765, 2024). "In addition, except for TIMP1 (P > 0.05), the expression levels of INHBA (P < 0.05), LAMC2 (P < 0.05), PLAU (P < 0.05) and TGFβ1 (P < 0.05) were significantly different between tumour and normal samples." (PMID 37325056, 2023). "Moreover, in mice co-transfected with both LAMC2 siRNA and EGFR plasmid, tumor size, volume, and weight were substantially reduced compared to the NC group." (PMID 37542131, 2023). "Moreover, we showed that silencing of either LAMC2 or EGFR generated direct opposite effects on colony growth, cell cycle progression, cell activity, apoptosis, and tumor growth." (PMID 37542131, 2023). "The function of EPHA2, LAMC2 and LOXL2 in tumor cells may explain the correlation between the VM score and poor prognosis of LUAD patients." (PMID 37351348, 2023). "The binding of TGF-β and SDF-1 to the membrane receptors on the tumor triggers the expression of endothelial markers like VE-cadherin, matrix metalloproteinase (MMP2) and laminin subunit gamma-2 (LAMC2) that could degrade the ECM to form VM." (PMID 37035187, 2023). "Tumors generated from LAMC2-EGFP+ cells were populated with LAMC2-EGFP+ and EGFP− tumor cells thus implying that LAMC2-expressing cells undergo self-renewal and differentiation during tumor formation and expansion." (PMID 36289544, 2022). "LAMC2, a target gene of miR-134, activates the EGFR/MAPK pathway but is also downregulated by miR-134, thereby inhibiting the migration and invasion of OSCC tumour stem cells by suppressing the PI3K-Akt signalling pathway." (PMID 35327656, 2022). "For discrimination of the normal and tumour sampling zones, we were able to derive an effective gene-based classifying model for molecular abnormality based on a panel of eight genes (MMP1, MMP12, MYO1B, TNFRSF12A, WDR66, LAMC2, SLC16A1 and PLAU)." (PMID 35327656, 2022). "Using data retrieved from our previous study, we demonstrated that the gene expression level of KRT13 was significantly down-regulated in OSCCs compared to their corresponding non-tumor epithelia, while the expression levels of KRT17, MKI67, and LAMC2 in OSCCs were significantly upregulated." (PMID 35524231, 2022). "Furthermore, shLAMC2 decreased tumor volume and the expression of LAMC2, Ki-67 and integrinβ1, but increased the expression of E-cadherin in LSCC tumor-bearing mice." (PMID 36284634, 2022). "For example, the labelling of distinct tumor cells with specific marker genes, which are not necessarily expressed at the cell surface such as LAMC2." (PMID 36289544, 2022). "Similarly, in early-stage tumor patients, PTX3 levels were higher than controls (**** p < 0.0001), indicating that both LAMC2 and PTX3 are already altered in the earliest stages of PDAC." (PMID 35681634, 2022). "Although SCC tumor cells are known to produce laminin-332 proteins, the expression levels of all laminin-332 genes (Lama3, Lamb3, and Lamc2) were similar between TGF-β-responding and nonresponding tumor cells in vivo." (PMID 31792062, 2019). "Uncoupled regulation, namely induction of the LAMC2 but not the LAMA3 gene in response to signals derived from the tumor stroma at the invasive front of tumors is an important issue in tumor biology." (PMID 18664273, 2008). "Furthermore, IVC suppresses the transcriptional activity of VE-cadherin, EphA2, MMP2/9/14, PI3K, and LAMC2, as well as the protein expression of VE-cadherin, EphA2, and MMP2/9, thereby blocking tumor cell adhesion, ECM degradation, and the maintenance of vascular-like structures in HCC." (PMID 41019994, 2025).
tumor (continued). "Besides, LAMC2, KRT8 and KRT19 spatially patterned tumor markers shared ‘epidermis development’ and ‘cellular component morphogenesis’ spatially patterned pathways in the tumor region, which may indicate the proliferation of cancer cells." (PMID 36243975, 2023). "We also found LAMC2, KRT8 and KRT19 spatially patterned tumor markers sharing ‘epidermis development’ and ‘cellular component morphogenesis’ spatially patterned pathways in the tumor region, which may indicate the proliferation of cancer cells." (PMID 36243975, 2023). "However, LAMC2 expression was independent of clinical variables such as gender, tumor differentiation, and primary site." (PMID 36284634, 2022). "Notably, we found p-EMT tumor cells (p-EMT sub-cluster) that highly expressed CDH1 (E-cadherin), keratin KRT14/16/17, TP63 (Tumor protein p63), and basement membrane ECM glycoprotein- Laminin family (LAMC2, LAMB3, LAMA3...)." (PMID 35742914, 2022). "Indeed, the tumor cores (L and LB) were found to express numerous pEMT genes at significantly greater levels than the TME, including the laminins (LAMC1, LAMC2, LAMA3), integrins (ITGA2, ITGB1, ITGAV), and inflammatory and neutrophil-attracting chemokines (CXCL8, CXCL1)." (PMID 36216799, 2022). "Therefore, we speculated that LAMC2 as an intermediate molecule of GPR115 regulated EMT progression, and inducing malignant phenotype of tumor." (PMID 33330053, 2020). "Additionally, cytokines in the tumor environment, such as TGF-β1 could induce LAMC2 expression." (PMID 37174083, 2023). "qRT-PCR of tumor tissues from metastatic and non-metastatic CRC patients also showed LAMC2 is higher expressed in metastatic CRC patients than in non-metastatic CRC patients." (PMID 38818308, 2024). "Both CM presented proteins involved in proliferation of both tumor and non-tumor cells, of which CAPN1, CST1, LAMC2 and RANBP3 stood out in CM3D and GPC6, ILK, MAPK1, MIF and PICALM in CM2D." (PMID 34884877, 2021). "The ROC analysis of LAMA3, LAMC2 and their combined expression in PDAC sets indicate that both genes display high accuracy in distinguishing between tumor and non-tumor tissues (the AUCs of the ROC curves were >0.70)." (PMID 31182680, 2019). "Results of the combined analysis suggest that serum level of LAMC2 and CA19-9 were higher in the PDAC patients than that of non-tumor patients/heathy donor from USA, German and Japan cohorts (p<0.05)." (PMID 31182680, 2019). "However, we observed that optiCA1 overexpressing tumor cells, when compared with the controls, had not statistically changed expression profile of mRNAs (COL1A1, COL4A4, LAMC2, CTHRC1, and WNT7B)." (PMID 31963697, 2020). "Similarly, gene expression of EPHA2, KDR, LAMC2, MMP1, and MMP14 did not vary between tumours of mice treated without and with aspirin." (PMID 32246008, 2020). "To further characterize tumor cells with and without GPA33 expression, we analyzed a subset of 14 CRC cases using double immunofluorescence and confocal microscopy for key cell state markers of WNT activity (β-catenin), EMT (LAMC2), differentiation (E-cadherin), and proliferation (Ki67)." (PMID 39472498, 2025).
cancer (127 papers, 2011 to 2025). A tumor composed of atypical neoplastic, often pleomorphic cells that invade other tissues. "Based on previous studies, LAMC2 has been implicated in the invasion and metastasis of various cancer types, such as colorectal, pancreatic, lung, cervical, and liver cancer, among others." (PMID 38703300, 2024). "Currently reported underlying mechanisms of LAMC2-induced cancer cell progression and metastasis include regulation of integrin B1-, ZEB1, and Snail expression, as well as activation of AKT1 and EGFR." (PMID 37542131, 2023). "LAMC2 levels have already been associated with poor prognosis in several human cancers due to its effects on cancer cell proliferation, migration and invasion." (PMID 36289544, 2022). "Given that LAMC2 encodes the most important chain of laminin-332 and it has been identified as a poor prognostic marker in some cancers 20, 21, the protein expression levels of LAMC2 in different ICC and HCC cells were evaluated using Western blot analysis." (PMID 33995623, 2021). "In particular, genes known to be associated with cancer such as LAMC2, UBE2C, AKT2, AKT2, BOK, MAP4, and FANCD2 were noted to be aberrantly spliced, indicating that the aberrant expression of CPSF1 significantly altered the ASEs of oncogenes in each dataset." (PMID 32437477, 2020). "Increase of LAMC2 has been shown in different kinds of cancers to further underline its role in carcinogenesis." (PMID 32397610, 2020). "LAMA3 and LAMC2 encode for products that are essential parts of laminin-322 (formerly known as laminin-5), which is known to stimulate cell migration in cancers and is related with the prognosis of diseases." (PMID 31182680, 2019). "The rs2147578 C > G polymorphism in the long non-coding RNA gene Lnc-LAMC2–1:1 is associated with increased susceptibility to a few types of cancers." (PMID 30285664, 2018). "Abnormal expression of LAMC2 was found in several types of cancer, and elevated expression of LAMC2 is associated with poor clinical outcome and relapse." (PMID 30285664, 2018). "LAMC2 has been implicated in the pathogenesis of cancers in increasing numbers of studies." (PMID 36284634, 2022). "Furthermore, blocking TGF-β signaling by silencing TGF-ΒR1 in HCC cells attenuates VE-cadherin/MMP-2/LAMC2 expression and inhibits cancer-associated fibroblast (CM-CAF)-promoted VM formation." (PMID 31772665, 2019). "Many hypoxia-upregulated genes, including COL1A1, COL5A1, COL6A3, LAMC2, and SERPINE1, are linked to enhanced migration, invasion, immune evasion, or treatment resistance in various cancers, including NSCLC." (PMID 41009714, 2025). "It has been reported that Laminin γ2 (LAMC2) is highly expressed in a variety of tumors, and its high expression is correlated with cancer development and progression." (PMID 38760717, 2024). "In cancer cells, knockdown LAMC2 promoted apoptosis, while its overexpression inhibited apoptosis, indicating that LAMC2 inhibited the occurrence of Tun-induced apoptosis via alleviating ER stress." (PMID 37891404, 2024). "Repression of LAMC2, however, elicited ER stress and impaired mitochondrial function, ultimately triggering apoptosis in cancer cells." (PMID 37891404, 2024). "This study provides new insights and highlights the promising potential of LAMC2 as a therapeutic target for cancer treatment." (PMID 37891404, 2024). "Human LAMC2 and ITGA6 are confirmed targets of miR-29 in cancer cells, where LAMC2 interacts with ITGA6 to improve focal adhesion formation and cell migration." (PMID 37981221, 2024). "Taken together, this study proposes that in mitigating ER stress in cancer cells, LAMC2 exerts an emergency stress-resistance response by binding to MYH9 and MYH10 to promote ER-mitochondria interaction around the nucleus." (PMID 37891404, 2024). "After forward search and backward search, we identified a set of five differentially expressed genes (LAMC2, TSPAN1, MYO1E, MYOF, SULF1) in Cancer/Normal that was optimized for diagnostic ability." (PMID 39850570, 2024).